FAM117B (family with sequence similarity 117 member B)
Synonyms: ALS2CR13; FLJ38771
Tractability: PROTAC: ubiquitination databases record sites on it; its protein half-life has been measured.
Gene: Protein-coding gene on chromosome 2 (202,634,969 to 202,769,757, forward strand). Ensembl gene ENSG00000138439.
Subcellular location (Human Protein Atlas): Nucleoplasm; Centrosome
Gene Ontology:
Molecular function: protein binding
Genetic constraint (gnomAD): Loss-of-function variants: 21 observed, 39.56 expected, observed/expected ratio (o/e) 0.53, 90% interval 0.38 to 0.76. The synonymous counts are far from expectation, so gnomAD's model fits this gene poorly and the ratio says little. Missense variants: 663 observed, 670.85 expected, observed/expected ratio (o/e) 0.99, 90% interval 0.93 to 1.05. Synonymous variants: 306 observed, 252.51 expected, observed/expected ratio (o/e) 1.21, 90% interval 1.1 to 1.33.
Homologues: Orthologues: chimpanzee FAM117B (99% identical), macaque FAM117B (99% identical), dog FAM117B (97% identical), pig FAM117B (97% identical), rat Fam117b (91% identical), mouse Fam117b (91% identical), tropical clawed frog fam117b (67% identical), zebrafish fam117bb (52% identical), zebrafish fam117ba (37% identical). Paralogues in human: GLCCI1 (45% identical), FAM117A (29% identical).
Diseases named in the same sentence as FAM117B in open-access papers:
FAM117B is named in the same sentence as 10 diseases in open-access papers, as found by Europe PMC text mining. Sharing a sentence is not in itself a finding about the gene and the disease. The quoted sentences say what the papers report.
gastric cancer (5 papers, 2023 to 2025). A primary or metastatic malignant neoplasm involving the stomach. "FAM117B has been implicated in the promotion of gastric cancer, particularly through pathways related to cell proliferation and resistance to apoptosis." (PMID 40863222, 2025). "The increased co-expression of Nrf2 and an Nrf2 activating protein, FAM117B, was found in the tumor tissue of patients with gastric carcinoma and was associated with a poorer prognosis." (PMID 39204185, 2024). "Moreover, FAM117B overexpression was significantly associated with a poor prognosis of patients with gastric cancer." (PMID 36719368, 2023). "FAM117B promotes gastric cancer cell proliferation and reduces their sensitivity to chemotherapeutic agents in an NRF2-dependent manner." (PMID 39941813, 2025). "It was found that FAM117B promotes the growth of gastric cancer by targeting the KEAP1/NRF2 signaling pathway." (PMID 41542087, 2025). "In this study, we reported that family with sequence similarity 117, member B (FAM117B), promoted the growth of gastric cancer cells and reduced the sensitivity of cells to chemotherapeutic drugs." (PMID 36719368, 2023). "Considering that KEAP1/NRF2 signaling is regulated by multiple mechanisms in tumor cells, further studies are needed to determine the importance of FAM117B-mediated regulation of KEAP1/NRF2 signaling in gastric cancer." (PMID 36719368, 2023). "Subsequently, we investigated the role of FAM117B in regulating the growth and chemoresistance of gastric cancer cells." (PMID 36719368, 2023). "FAM117B activates KEAP1/NRF2 signaling by decreasing ubiquitin-proteasome degradation of NRF2 in gastric cancer cells." (PMID 36719368, 2023). "FAM117B promotes the chemoresistance of gastric cancer cells via regulation of KEAP1/NRF2 signaling." (PMID 36719368, 2023). "Subsequently, we investigated the role of the ETGE motif of FAM117B in regulating the growth and chemoresistance of gastric cancer cells." (PMID 36719368, 2023). "Our studies reveal the mechanism by which FAM117B promotes the growth and chemoresistance of gastric cancer and may provide a novel therapeutic target for gastric cancer." (PMID 36719368, 2023). "FAM117B promotes the growth of gastric cancer cells via regulation of KEAP1/NRF2 signaling." (PMID 36719368, 2023). "Considering the crucial roles of FAM117B in gastric cancer, developing small-molecule inhibitors for it may provide a new approach to treating gastric cancer." (PMID 36719368, 2023). "The higher protein level of FAM117B in gastric cancer could compensate for the lower affinity between FAM117B and KEAP1." (PMID 36719368, 2023). "Restoring FAM117B expression could abolish FAM117B knockdown–induced NRF2 protein inhibition in gastric cancer cells." (PMID 36719368, 2023). "Next, we studied how FAM117B regulates NRF2 protein levels in gastric cancer cells." (PMID 36719368, 2023). "FAM117B activates KEAP1/NRF2 signaling in gastric cancer cells." (PMID 36719368, 2023). "Yet we found that the protein level of FAM117B in gastric cancer was higher than that of NRF2." (PMID 36719368, 2023). "FAM117B promotes the growth and chemoresistance of gastric cancer cells." (PMID 36719368, 2023). "In addition, future studies are needed to investigate how FAM117B protein is upregulated in gastric cancer to better understand its molecular mechanism." (PMID 36719368, 2023). "FAM117B competes with NRF2 for KEAP1 binding in gastric cancer cells." (PMID 36719368, 2023). "Collectively, our findings reveal that FAM117B is involved in promoting gastric cancer growth and drug resistance, and it could be exploited as a cancer therapeutic target." (PMID 36719368, 2023). "We hypothesized that the higher protein level of FAM117B in gastric cancer could compensate for the lower affinity between FAM117B and KEAP1." (PMID 36719368, 2023). "Our study showed that FAM117B protein levels were elevated in human gastric cancer samples." (PMID 36719368, 2023).
gastric cancer (continued). "Moreover, FAM117B-induced growth and chemoresistance of gastric cancer cells were NRF2 dependent." (PMID 36719368, 2023). "We then investigated whether FAM117B regulates KEAP1/NRF2 signaling in gastric cancer cells." (PMID 36719368, 2023). "Next, the IHC assay was used to detect the protein levels of FAM117B and NRF2 of tumor tissue and adjacent normal tissues in gastric cancer microarrays (SOB cohort and AFB cohort)." (PMID 36719368, 2023). "We found that FAM117B and NRF2 protein levels were highly expressed in tumor tissues of patients with gastric cancer and their co-overexpression represented an independent factor for poor prognosis." (PMID 36719368, 2023). "The ETGE motif of FAM117B activates KEAP1/NRF2 signaling and promotes the growth and chemoresistance of gastric cancer cells." (PMID 36719368, 2023). "FAM117B and NRF2 are both overexpressed in gastric cancer tissues, and their co-overexpression represents a factor for poor prognosis." (PMID 36719368, 2023). "The protein levels of FAM117B and NRF2 in tumor tissues and matched adjacent normal tissues of gastric cancer patients were detected by Western blot." (PMID 36719368, 2023). "The Spearman correlation analysis indicated a significant correlation between the IHC scores of FAM117B and NRF2 in gastric cancer tissues." (PMID 36719368, 2023). "In this study, we found that FAM117B disrupted KEAP1-NRF2 interaction through its ETGE motif, which reduced the degradation of NRF2 and activated KEAP1/NRF2 signaling, and ultimately promoted the growth and chemoresistance of gastric cancer cells." (PMID 36719368, 2023). "Our findings revealed that FAM117B could bind KEAP1 to upregulate NRF2, then attenuated the sensitivity of gastric cancer to chemotherapeutic drugs." (PMID 36719368, 2023). "We also found that FAM117B overexpression downregulated ROS levels in shControl–gastric cancer cells, but not in NRF2-silenced cells, indicating that FAM117B induces NRF2 to regulate ROS levels in gastric cancer cells." (PMID 36719368, 2023). "Therefore, it was not surprising that FAM117B competed with NRF2 to bind KEAP1 in gastric cancer cells, changed the conformation of the KEAP1/NRF2 complex, and inhibited the ubiquitination degradation of NRF2." (PMID 36719368, 2023). "Whether and how FAM117B participates in the progression of gastric cancer cells are not clear." (PMID 36719368, 2023).
sarcoidosis (4 papers, 2017 to 2025). Sarcoidosis is a multisystemic disorder of unknown cause characterized by the formation of immune granulomas in involved organs. "According to Fischer's study, FAM117B was identified as the immune related factors associated with sarcoidosis in European populations." (PMID 35685372, 2022). "Relatively little is known about the function of FAM117B with the exception that it is a risk factor for sarcoidosis." (PMID 29253856, 2017). "Similarly, rs6748088 in FAM117B has been associated to sarcoidosis risk." (PMID 38390497, 2023). "Overall, SNPs from the following genes have already been identified in previous studies on sarcoidosis (GWAS or other): CCDC88B, ANXA11, IL23R, FAM117B, CCL24, ATXN2/SH2B3." (PMID 41466414, 2025).
migraine (2 papers, 2023). "For example, of the five genes (CARF, ICAIL, NBEAL1, FAM117B, and WDR12) at the rs138556413 locus, ICAIL and NBEAL1 have the strongest TWAS p value with migraine as compared to other genes." (PMID 37245199, 2023). "Furthermore, nine significant tissue–gene pairs were found for migraine and UACR using GTEx tissues, including four genes (NBEAL1, FAM117B, ICA1L) mainly expressed in tissues of the nervous and cardiovascular system." (PMID 37306871, 2023).
breast carcinoma (1 paper, 2023). "FAM117B is highly associated with bone formation and contribute to the metastasis of breast cancer to bone." (PMID 37426414, 2023).
cerebral small vessel disease (1 paper, 2022). Cerebral small vessel disease is the term currently used to pathological processes that affect the brain parenchymal circulation (arterioles, capillaries, and veins). "SNP rs116426890 is intronic to ABI2 and is linked to the expression of CARF, ICA1L, FAM117B, and NBEAL1 which are associated with both white matter hyperintensities and fractional anisotropy, predictors of cerebral small vessel disease which is involved in strokes and vascular dementia." (PMID 36684006, 2022).
tumor (4 papers, 2020 to 2024). "While little is known about the function of Fam117b, Slc7a11 downregulation is associated with RT-induced ferroptosis in tumor cells." (PMID 34364390, 2021). "Subsequently, tumor samples were divided into 2 groups, low FAM117B protein level and high FAM117B protein level, and NRF2 protein levels in these 2 groups were analyzed." (PMID 36719368, 2023). "Four missense variants were heterozygous in the tumor sample and not present in blood (FAM117B, CTNNB1, CELSR3 and STXBP5L)." (PMID 33379206, 2020). "Patients with high FAM117B and high NRF2 IHC scores in tumor tissues had the shortest overall survival." (PMID 36719368, 2023).
FAM117B also shares sentences with these, for which no sentence is quoted: cancer (1 paper); hepatocellular carcinoma (1); Stroke (1); vascular dementia (1).